IL4 (interleukin 4)
Diseases named in the same sentence as IL4 in open-access papers (continued):
Sharing a sentence is not in itself a finding about the gene and the disease.
glioblastoma (28 papers, 2007 to 2025). The most malignant astrocytic tumor (WHO grade IV). "In their previous paper there was only a suggestive relationship between IL4 and risk of glioblastoma, however this was with decreased levels with IL4 less than or equal to 5 years before diagnosis." (PMID 37265788, 2023). "In addition, ≤ 5 years before diagnosis, we observed associations between IL4 (OR = 0.82, 95% CI = 0.66, 1.01), sIL4RA (OR = 0.80, 95% CI = 0.65, 1.00), their interaction (OR = 1.06, 95% CI = 1.01, 1.12) and glioblastoma." (PMID 26352148, 2015). "In one work, the effect of IL-4-fused PE NBI-3001 exotoxin was studied in 25 patients diagnosed with glioblastoma multiforme." (PMID 35744957, 2022). "It was used against IL-4-expressing glioblastoma as an intratumoral infusion and other cancer cells expressing IL-4 receptor." (PMID 35744957, 2022). "Interferon-γ (IFNγ), tumor necrosis factor-α (TNFα), granzyme B, and IL-4 levels were significantly increased in iNKT cells stimulated with the α-GalCer-pulsed glioblastoma cell lines in a CD1d-dependent manner." (PMID 33128583, 2021). "The IL-4 induced microglial phenotype shares some similarity with the glioblastoma (IL-4 secreting cells)-induced tumor-supportive microglial phenotype, including the increased expression of Arg1 gene." (PMID 34082793, 2021). "Expression of IL4, an immunomodulatory cytokine, is increased in a glioblastoma cell line where it is thought to be a component of tumor-induced immunosuppression." (PMID 28594935, 2017). "For example, in glioblastoma patients, levels of the immunosuppressive cytokines IL4 and IL10 were elevated in both their peripheral lymphocytes and cell cultures from their tumors." (PMID 28594935, 2017). "On the other hand, elevated IL-4 levels may suggest that fluoride may have a potentially inhibitory effect on glioblastoma progression and invasiveness." (PMID 40497976, 2025). "Kaplan–Meier analysis of 540 glioblastoma cases from the Glioblastoma tumor RNA-Sequence dataset we identified showed a negative association between levels of gene expression of IL-4, IL-10, CCL-2, GM-CSF, and VEGF and overall survival." (PMID 35884700, 2022). "Besides, IL-4 can also abnormally activate STAT3 in glioblastoma (GBM) cells, which are related to the expression of IL-13Rα2." (PMID 33013320, 2020). "Furthermore, M(GM-CSF) were found to be more phagocytic than M(IL-4 + IL-13) towards primary human glioblastoma cells in the context of CD47 blockade ex vivo." (PMID 29084248, 2017). "IL-4 fused with Pseudomonas exotoxin is in Phase I clinical trials in patients with glioblastoma." (PMID 20331869, 2010). "For instance, compared to traditional 2D glioblastoma cultures, extracellular vesicles released by 3D tumor organoids displayed a higher abundance of miRNAs involved in immunoregulatory signaling, such as interleukin-4 (IL-4) and interleukin-13 (IL-13) cytokine pathways." (PMID 40806235, 2025). "Two reports, in glioblastoma and lung epithelial cells, showed interactions between the cytoplasmic domains of IL13RA2 and IL4R that interfere with IL4-driven STAT6 signaling." (PMID 40663259, 2025). "Glioblastoma EVs in the tumor microenvironment then stimulate local astrocytes to produce cytokines including CSF2 and 3, IL-4, -6, -10, and -13, which together promote a T-helper type 2 immunosuppressive phenotype." (PMID 38188300, 2023). "We conducted expression profiling of CD274 (PD-L1), GATA3, IFNG, IL12R, IL12RB2, IL4, PDCD1 (PD-1), PDCD1LG2 (PD-L2), and TBX21 (T-bet) using data of 158 glioblastoma multiforme (GBM) patients with clinical information available at The Cancer Genome Atlas." (PMID 29721184, 2018). "We demonstrated that these glioblastoma cells were put into relatively cytokine "rich" environment produced by AT-MSC containing IL-1β, IL-1ra, IL-2, IL-4, IL-6, IL-8, TNF-α, IFN-γ, CCL5, CCL26, CXCL10, PDGF-bb." (PMID 20509882, 2010).
lung diseases (28 papers, 2009 to 2025). "Th2 cells mainly produce interleukins (IL)-4, IL-5, and IL-13, which promote eosinophil recruitment and contribute to the development of Th2-associated lung disease." (PMID 40026847, 2025). "Th2 cytokines IL-4 and IL-13 have been implicated in altered lung function in various pulmonary disease models and in promoting airway goblet cell hyperplasia." (PMID 21660239, 2011). "The signaling events that drive the SP-A-dependent amplification of IL-4 effects on alveolar macrophages may aid in the development of new approaches to control lung diseases caused by exaggerated repair responses." (PMID 35444643, 2022). "Also, some cytokines, for instance IL-4 or IL-13, which are implicated in various lung disorders, also behave as inducers of arginase." (PMID 28974751, 2017). "In addition to an increased IL-17 response to the lysate in CF/ABPA/CPA patients (median, 14.3 versus 1.3 pg/mL in controls), significantly greater induction of the Th2 cytokines IL-4 and IL-5 was found in samples from patients with Aspergillus-associated lung diseases." (PMID 34201183, 2021). "By combining IL-4 and IL-13, we created a more comprehensive model that reflects the complexity of inflammatory processes in lung diseases." (PMID 40370530, 2025). "IL-4 and IL-17 promote inflammation and fibrosis in systemic sclerosis, pulmonary disease, and liver cirrhosis." (PMID 37524866, 2023). "Among these Th2 cytokines, IL-4 and IL-13 particularly promote fibrosis, and indeed, IL-4 and IL-13 levels are increased in many lung diseases." (PMID 36016937, 2022). "BAL and plasma of patients with pulmonary TB contained increased levels of IL-4 compared to patients with other lung diseases, patients with moderate-advanced TB had higher levels of IL-4 compared to patients with mild TB disease." (PMID 25803478, 2015). "Accordingly, increased IL-4 expression and polymorphism in the IL-4 gene has been correlated with severe RSV lung disease findings consistent with IL-4 mediated differentiation of CD4+ T cells toward Th2-type cells." (PMID 24040360, 2013). "In P. brasiliensis-infected C57BL/6 mice, IL-4 neutralization leads to less severe pulmonary disease, low production of Th2 cytokines, high TNF-α and IL-12 synthesis, and low IgG1 antibodies levels." (PMID 19229338, 2009). "Neutralization of pro-inflammatory cytokines such as IL-6, TNF-α, VEGF, and IFN-α/β, as well as anti-inflammatory IL-4, during severe pulmonary disease may help reduce ongoing parenchymal damage in the MTB-infected lung." (PMID 28125719, 2017). "However, the patients with moderate and advanced pulmonary disease were having enhanced levels of cytokines IL4 and IL-10 in contrast to mild disease patients." (PMID 27819024, 2016). "TCF7 interacts with multiple proteins and target genes (e.g. CD3E, β-catenin, TCF7L2, LEF-1, IL-17, IL-4, or Eomes) and is involved in several signal pathways (e.g. Wnt, FoxO1, Notch, or P21pathways) which are critical for lung diseases, especially the canonical Wnt/β-catenin pathway." (PMID 26289446, 2015). "Activation of the A2BR can also promote the expression or release of pro-inflammatory cytokines such as IL-4, IL-8 and IL-13, which may influence the chronic nature of certain lung diseases." (PMID 20169073, 2010). "It has been shown that, in comparison to healthy individuals, the patients with mild, moderate, or advanced pulmonary disease were having enhanced levels of IFN-γ, IL-2, IL-4, and IL-10." (PMID 27819024, 2016). "The pre-treatment levels of IL-4 and IL-13, secreted from Th2 cells, were significantly lower in patients with MABC lung disease than in control subjects." (PMID 25295870, 2014). "Furthermore, in our in vivo experiments, LPS-mediated TLR4 signaling in iNKT cells enhanced IFN-γ production but reduced IL-4 levels in the lungs of mice with HP or BIPF, resulting in the regulation of these pulmonary diseases." (PMID 23028952, 2012).
lung diseases (continued). "Therefore, the interaction between IL-4 and TSLP could contribute to the development of these lung disorders." (PMID 34440780, 2021). "Thus, early polarization towards an increased IL-4/IFN-γ ratio could be a mechanism behind air pollution-enhanced influenza virus levels and the observed increase in lung disease." (PMID 21092162, 2010).
Alzheimer disease (27 papers, 2012 to 2026). A progressive, neurodegenerative disease characterized by loss of function and death of nerve cells in several areas of the brain leading to loss of cognitive function such as memory and language. "For example, IL-4 treatment facilitates autophagy-dependent M2 microglial polarization and inhibits amyloid-β-induced M1 microglial polarization in Alzheimer's disease." (PMID 38745316, 2024). "Using an animal model for Alzheimer’s disease, it was also reported that AD-16 improved short-term and long-term memory, restored the IL-4 and IL-6 levels in the brain, and protected neurons." (PMID 39736920, 2024). "Others have reported that AD-16 was able to reduce IL-1β expression induced by LPS in vivo, restore IL-4 and IL-6 levels in a mouse model of Alzheimer’s disease, and reduce IL-1β and TNF-α levels in the brain of ischemic mice." (PMID 39736920, 2024). "IL-4 has been shown to have neuroprotective effects in several models of neurodegeneration, including Alzheimer’s disease and Parkinson’s disease." (PMID 37175946, 2023). "The protective effect of IL-4 has also been demonstrated in a mouse model of Alzheimer’s disease, where the injection of IL-4 alone or of IL-4 + IL-13 induced the proliferation of Arg1+ microglia and the clearance of plaques in APP/PS1 mice." (PMID 37429945, 2023). "In other work, the IL-4 deficiency was shown to impair the expression of CD200 and CD200R in activated lymphocytes in patients with Alzheimer’s disease." (PMID 33804413, 2021). "But, on the other hand, one study described an increase in amyloid pathology possibly due to IL-4 inhibiting microglia from properly scavenging Aβ in Alzheimer’s disease mouse model." (PMID 30669620, 2019). "Interleukin-4, the prototypic M2 inducing cytokine, has been shown in several cases to mitigate Alzheimer’s disease pathology." (PMID 24889886, 2014). "CNS expression of anti-inflammatory cytokine interleukin-4 attenuates Alzheimer's-disease-like pathogenesis in APP+PS1 double-transgenic mice, enhances neurogenesis, and inhibits spatial learning impairment." (PMID 23841061, 2013). "In addition, research on Alzheimer’s disease and epilepsy in children has also found a correlation between IL-4 and CD200/CD200R expression." (PMID 37761997, 2023). "The authors suggested that IL-4 may play a beneficial role against Alzheimer’s disease because pretreating microglia with IL-4 induced autophagy that partly contribute to increase in amyloid-β uptake and degradation." (PMID 33066678, 2020). "We believe that this is not the case because in our previous studies where we block neurogenesis using pathological hallmarks of Alzheimer’s disease and Kynurenic acid, interleukin-4 was sufficient to restore the neurogenic capacity at the later time points of the culture." (PMID 30809125, 2019). "In our previous model of Alzheimer’s disease, reduced neurogenic response could be restored by using interleukin-4 as a stimulant of neurogenic competency and neurogenesis in primary human cortical astrocytes." (PMID 30809125, 2019). "This study shows that serotonergic neurons alter neural stem cell proliferation and neurogenesis via a complex neuron-glia interaction involving interleukin-4, BDNF and NGF receptor in a zebrafish model of Alzheimer's disease." (PMID 31905199, 2020). "In Alzheimer disease patients, increased levels of Th1 cytokines such as IFN-γ, and decreased levels of Th2 cytokines such as IL-4 have been found." (PMID 23204981, 2012). "In controls, cortical perfusion declined with increasing IFN-γ, IL-2, IL-4, IL-6, IL-10, IL-12p70, IL-13 and tumour necrosis factor-α (TNF-α) but these relationships were lost with progression of Alzheimer’s disease, and with infection (even in Braak stage 0–II brains)." (PMID 33723589, 2021).
Alzheimer disease (continued). "Intracerebral microinjection of a mixture of IL-4 and IL-13 effectively restored spatial memory and learning abilities in C57BL/6 mice with overexpression of the amyloid-protein precursor 23 gene (AβPP23) (Alzheimer’s disease) through the increase of the IL-4 content in the hippocampus." (PMID 32778140, 2020).
nematode infection (27 papers, 2010 to 2025). "Number of studies have been conducted on functional significance of IL-4 polymorphisms in different diseases worldwide, to our knowledge this is the first study conducted in Pakistan where we investigated the role of IL-4 variants against nematode infection in the local population." (PMID 36407356, 2022). "In the current study, screening of exon 2, 3, 4, 5 and flanking regions of IL-4 gene was done to find the polymorphisms which might be linked with susceptibility to nematode infections." (PMID 36407356, 2022). "Due to an intense IL-4 response, macrophages acquire AAMs rewiring which in nematode infections act in concert with peristalsis to ultimately expel worm parasites." (PMID 38842647, 2024). "The production of IL-4 and IL-13 during nematode infection in vivo is mainly initiated by the alarmins IL-25, IL-33 and TSLP released by epithelial and stromal cells." (PMID 38414039, 2024). "In response to nematode infection, mast cells also produce Th2-type cytokines such as IL-13, IL-4, and IL-5, which contribute to the recruitment of inflammatory cells such as eosinophils, natural killer (NK) cells, and neutrophils to the mucosal sites." (PMID 38338687, 2024). "Collectively these data show that CD4+ T cell activation in the lymph nodes followed by entry to the pleural space are required for the expansion and M(IL-4) polarization of tissue-resident LCMs in nematode infection." (PMID 36948193, 2023). "IL4 is regarded as a prominent feature of the Th2-dominated immune response and plays an important role in preventing parasitic nematode infection." (PMID 31164173, 2019). "Interleukin 4 (IL4) is a classic T-helper cell type 2 (Th2)-type cytokine that plays an irreplaceable role against nematode infection." (PMID 31164173, 2019). "Many studies have suggested that nematode infection can induce a Th2 response and result in strong IL4 production." (PMID 31164173, 2019). "IL-4- or IL-13-induced alternative macrophage polarization occurs in a number of pathological processes including nematode infection, tumor development, lung inflammation, and fibrosis." (PMID 29343442, 2018). "Nematode infection induces polarized type 2 immunity characterized by increased expression of cytokines such as IL-4, IL-5, IL-13, and IL-25." (PMID 26377648, 2015). "Host defense against nematode infection relies on Th2 cytokines IL-4 and IL-13 activating STAT6 signaling pathways, which then leads to up-regulation of various downstream effector molecules as well as stereotypic alterations in gut function." (PMID 26377648, 2015). "In contrast, up-regulation of the Th2 cytokines, IL-4 and IL-13, during nematode infection and allergy leads to development of alternatively activated macrophages (M2) that are important for tissue repair." (PMID 24465430, 2014). "RELM-β is increased significantly by nematode infection and is necessary for IL-4/IL-13-dependent expulsion of enteric nematodes." (PMID 24465430, 2014). "The host response to nematode infection is characterized by induction of a T-helper 2 (Th2) immune response, involving the elevated production of inteleukin-4 (IL-4), IL-5, IL-10 and IL-13." (PMID 24465430, 2014). "Recently, we described that nematode infection induced an IL-4/IL-13-driven intestinal smooth muscle hypercontractility, which was absent in global IL-4Rα−/− mice and reduced in smooth muscle cell-specific IL-4Rα−/− mice." (PMID 23284939, 2012). "On the other hand, Th2 cells play a central role in mediating the protective immunity against parasitic nematode infections by releasing an array of cytokines, such as IL-4 and IL-13." (PMID 21414188, 2011). "The intensity of nematode infections differed significantly between IL4 genotypes: individuals of genotype T/T had higher parasite egg outputs than individuals of the more frequent genotypes C/T and C/C (t24,2 = 2.20, p CC-TT = 0.04, p CT-TT = 0.04)." (PMID 21501512, 2011).
nematode infection (continued). "The classical response to nematode infection in mammals is a Th2-like response with a predominant IL-4 production." (PMID 20356390, 2010). "In addition, IL-13 and IL-4 increase smooth muscle contractility in the gut during nematode infections." (PMID 38338687, 2024). "To determine whether the nematode infection-regulated Vegfa and Flt1 mRNA expression are IL-4 dependent, we investigated their expression levels in thioglycolate and nematode-elicited peritoneal macrophages derived from Il4ra-/-mice." (PMID 37215144, 2023). "For nematode infections, Ox40L-/- mice have been shown to exhibit impaired adult worm expulsion, and weaker IL-4 and IgE responses to secondary H. polygyrus infection, confirming Ox40/Ox40L interactions as important for efficient host recall responses to intestinal parasitic nematodes." (PMID 35418979, 2022). "Hence, further work addressing the role of Th2/1 hybrid cells in the context of natural GI nematode infections is needed and the profiles of IL-4/IFN-γ expression by porcine Ascaris-specific CD4+ T cells are currently under investigation in our group." (PMID 35690651, 2022). "It has been observed in our study that all these patients were suffering from severe infection and suggested that the IL-4 might play a regulatory role in the pathogenesis of nematode infections in these patients." (PMID 36407356, 2022). "Indeed, the combinatorial action of both CSF1 and IL‐4 is required to control macrophage numbers within the peritoneal cavity during nematode infection." (PMID 27592711, 2016). "The pathways including WNT/β-catenin signaling, Th1 and Th2 activation, RAR activation, NGF-stimulated transcription, IL-15 production, and IL-4, 7, 12, and 13 signaling are the top pathways that the nematode infection elicits, which could lead to eventual protection or immune evasion." (PMID 39795948, 2024). "Mice deficient for its only known ligand Ox40L (Ox40L-/- mice) show impaired adult worm expulsion, lower IL-4 production and parasite-specific IgE responses following a secondary H. polygyrus infection, highlighting Ox40-Ox40L interactions as key for host immunity to a challenge nematode infection." (PMID 35418979, 2022). "Following nematode infection, Tuft cells in the intestinal epithelium secrete IL-25; this activates ILC2 which secrete IL-4 and IL-13." (PMID 40565065, 2025). "Gene set enrichment analysis (GSEA) showed that the in vitro IL-4-repressed gene set was significantly enriched (FDR q-value < 0.1, NER: −2.38) among the genes that were downregulated in response to nematode infection in peritoneal macrophages." (PMID 29343442, 2018). "The suppressive effects of M(IL-4) MΦ on T-cell proliferation have been reported in the literature where M(IL-4) cells prevented proliferation of EL4 and D10.G4 T cells through an undefined cell-contact-dependent mechanism during nematode infection." (PMID 29250063, 2017). "TFF3 is IL-4/IL-13-regulated and interacts with the mucin MUC2 (not on array) to alter mucus viscosity, with which it co-localises in human intestinal goblet cells, and up-regulation of both these mucus components has been associated with responses to nematode infection in mice." (PMID 21682880, 2011).